EPCAM (epithelial cell adhesion molecule)
Diseases named in the same sentence as EPCAM in open-access papers (continued):
Sharing a sentence is not in itself a finding about the gene and the disease.
ovarian carcinoma (continued). "We identified one case of MPE, originating from an ovarian cancer patient, where a substantial proportion of the EpCAM+ cells were co‐stained for CD45." (PMID 40525275, 2025). "CAR-T cells targeting EpCAM, which is upregulated in ovarian cancer, CRC, and peritoneal carcinomatosis, have shown remarkable success in eliminating EpCAM-expressing cancer cells." (PMID 40647402, 2025). "Confocal microscopy imaging of fixed omental tissue confirmed the presence of human ovarian cancer cells based on the binding of anti-epithelial cell adhesion molecule (EPCAM) antibody." (PMID 41322193, 2025). "Previous studies have utilized multiantibody-modified magnetic nanoparticles targeting MSLN, EpCAM, and N-cadherin for the isolation and molecular analysis of circulating tumor cells in epithelial ovarian cancer." (PMID 40792273, 2025). "We observed that the downregulation of this gene led to an increase in the death of EpCAM + cells in the ovarian cancer cell lines studied." (PMID 38807192, 2024). "IL-8 has the capacity to enhance the expression of EpCAM in ovarian cancer cells, while conversely, IL-6 exerts an inhibitory effect on this specific phenomenon." (PMID 38187284, 2024). "The exploration of EpCAM-targeted therapies, such as the bispecific T-cell engaging antibodies (BiTE) that show efficacy against ovarian cancer cells, underscores the potential of EpCAM as a target for innovative therapeutic interventions." (PMID 39033780, 2024). "One of the first publications devoted to CTCs identified them in the blood of 12% of ovarian cancer patients, using an immuno-microbead that recognized an EpCAM, regularly expressed on ovarian cancer cells." (PMID 38275400, 2024). "EpCAM expression was also significantly higher in epithelial ovarian cancer tissues than in normal ovarian tissues." (PMID 38833451, 2024). "In ovarian cancer, EPCAM is often highly expressed in malignant tumors, correlating with poor prognosis." (PMID 40836974, 2024). "Epithelial cell adhesion molecule (EpCAM) expression is upregulated in most epithelium-derived tumors; however, studies on prognostic value of EpCAM overexpression in ovarian carcinoma have shown contradictory results." (PMID 38928484, 2024). "The elucidation of EpCAM’s role in ovarian cancer presents a transformative insight into the mechanisms of tumor aggression and chemoresistance." (PMID 39033780, 2024). "In ovarian cancer, studies on EpCAM overexpression in tumor tissue and survival have shown contradictory results." (PMID 38928484, 2024). "Ovarian cancer cell lines with high EpCAM expression have been shown to be resistant to T-cell-mediated killing; however, following incubation with solitomab (1 μg/mL), they became highly sensitive to T-cell-mediated killing." (PMID 38612911, 2024). "To date, only a small number of studies of EpCAM-positive EVs has been conducted on clinical samples of ascites or plasma of ovarian cancer patients." (PMID 38928484, 2024). "Detection of a panel of biomarkers (EGFR, CA125, EGFR2, folate receptor α, CD9, CD24, and EpCAM) in circulating exosomes not only identified ovarian cancer patients from control subjects but also distinguished between early- and advanced- stage ovarian cancer." (PMID 38796525, 2024). "EpCAM+ ovarian cancer cell lines established from patients with chemotherapy-resistant disease (OSPC-ARK-1, OSPC-ARK-2, OSPC-ARK-4, CC-ARK1, and CC-ARK-2) treated with 5 μg/mL of adecatumumab displayed increased cytotoxicity compared to control." (PMID 38612911, 2024). "There were also phase II clinical trials completed in EpCAM-positive solid tumors, such as gastric and ovarian cancers, with favorable outcomes and acceptable side effects." (PMID 38791091, 2024). "Analysis of a combination of CD24 and EpCAM with CA125 as tumor-dervied exosomal markers improved the accuracy for early diagnosis of ovarian cancer." (PMID 38796525, 2024).
ovarian carcinoma (continued). "One of the most studied EVs’ cargo proteins in ovarian cancer is epithelial cell adhesion molecule (EpCAM, also known as CD326), a transmembrane glycoprotein involved in cell proliferation and differentiation." (PMID 38928484, 2024). "In both ovarian cancer cell lines, we observed that downregulating HOOK1 caused a decrease in the percentage of EpCAM + cells compared to that of parental cells." (PMID 38807192, 2024). "The CTCs marked as CD45-/HE4+EpCAM+cytokeratin+vimentin+ cells were increased in ovarian cancer patients and showed positivity in 49% of patients with a sensitivity of 73%, higher than that for CA125." (PMID 38275400, 2024). "Metastatic and recurrent/chemotherapy-resistant ovarian cancers showed significantly higher levels of EpCAM expression than primary ovarian carcinomas." (PMID 38833451, 2024). "In another study, CTCs were isolated on the base of EpCAM/CK positivity combined with physical cellular features like cell size and deformability in patients with benign and malignant ovarian tumors." (PMID 38275400, 2024). "Then, we determined a modest (∼20%) but significant killing effect of BIX02189 treatment when compared with untreated control in the survival of EpCAM+ primary ovarian cancer cells." (PMID 37029785, 2023). "Juan Fu found that the EpCAM target is highly upregulated in actual ovarian cancer samples and sought to construct 3rd -generation EpCAM CAR T cells and then verified their antitumor activities in vitro and in vivo." (PMID 36707873, 2023). "Previously, the EpCAM-targeting toxin fusion protein Ec1–LoPE (43 kDa) was studied in prostate cancer cells, ovarian cancer cells, and breast cancer cells for its cytotoxic effect." (PMID 36769161, 2023). "By using ExoSearch, it was shown that ovarian cancer patients overexpressed the CA-125, EpCAM, CD9, CD81 and CD63 markers." (PMID 37504087, 2023). "According to the results of the immunohistochemistry analysis, the expression level of EpCAM in ovarian cancer tissue is remarkably higher than its expression in ovarian para-cancerous tissues." (PMID 38146364, 2023). "A type I transmembrane glycoprotein, the epithelial cell adhesion molecule (EpCAM), regulates intercellular adhesion and has been suggested to be present on ovarian cancer cells." (PMID 38201468, 2023). "The nPLEX assay was able to distinguish between exosomes from ovarian cancer patients with elevated protein expression of EpCAM and CD24 in comparison with non‐cancer patients." (PMID 35898167, 2023). "assessed the expression of THY1 and EpCAM on a number of primary ovarian cancer patient-derived samples using high-content imaging." (PMID 38146364, 2023). "Briefly, these researchers first assessed the expression of EpCAM on ovarian cancer cell lines and patient-derived samples." (PMID 38146364, 2023). "Here, we demonstrate that bsAb CD73xEpCAM has potent capacity to inhibit the CD73/adenosine immune checkpoint exposed on ovarian cancer cells in an EpCAM-directed manner." (PMID 37509310, 2023). "It showed that DNA methylation changes of CDH1, EPCAM and TWIST2 genes underlie the EMT induction in cisplatin resistant ovarian cancer cell line." (PMID 35523936, 2022). "One possible explanation is the downregulation of EpCAM during EMT or the heterogeneous expression of cell surface markers in ovarian cancer." (PMID 35545786, 2022). "Two cargo proteins, CD24 and EpCAM, were found in exosomes from malignant ascites of patients with ovarian cancer." (PMID 36741380, 2022). "To test one of the identified candidate pairs, we generated ovarian cancer cells co-expressing EPCAM and THY1 in combination with eGFP." (PMID 35115587, 2022). "CD24 and epithelial cell adhesion molecule (EpCAM) proteins were identified in exosomes purified from ascites fluid of ovarian cancer patients." (PMID 35024437, 2022). "We found that EPCAM was reliably expressed on all ovarian cancers, showing a high coverage of cells in individual ovarian cancer samples." (PMID 35115587, 2022).
ovarian carcinoma (continued). "A PLGA nanofiber-based microfluidic device was fabricated with dual aptamer-targeting EpCAM and N-cadherin proteins, and 1 to 13 CTCs were successfully detected in 3 mL blood samples of ovarian cancer patients." (PMID 35323454, 2022). "We identified THY1 with a characteristic expression on non-epithelial cells like fibroblasts and co-expression with EPCAM on ovarian cancer cells." (PMID 35115587, 2022). "Various cancer biomarkers associated with ovarian cancers have been considered for the design of tumor-targeting agents, including the folate receptor, VEGF, EGFR, HER2, epCAM, PSMA, and αvβ3 integrin." (PMID 35625796, 2022). "The same research group also developed a high-throughput screening method that distinguishes ovarian cancer patients with a high degree of accuracy by targeting epithelial cell adhesion molecule (EpCAM) and CD24 on EVs in ascites." (PMID 35672766, 2022). "In ovarian cancer, the level of EpCAM positive EVs has been shown to correlate with severity of disease." (PMID 35012489, 2022). "Previous studies showed that EpCAM+/CD45+ ovarian cancer acquired a more aggressive and drug-resistant phenotype by upregulating downstream effectors of PI3K/AKT signaling." (PMID 36369033, 2022). "One ovarian cancer patient (Ov1) plasma was clearly positive for EpCAM+-CD81+ EVs, followed by a moderate signal in samples from Br1 and Br2 patients and lower signals were observed for the rest of the patients." (PMID 35135541, 2022). "Recent studies have illustrated that exosomes derived from ovarian cancer contain miRNA, EpCAM, CD24, and other molecules." (PMID 36741380, 2022). "With MICS we analysed human glioblastoma, ovarian and pancreatic carcinoma, and 16 healthy tissues, identifying the pair EPCAM/THY1 as a potential target for chimeric antigen receptor (CAR) T cell therapy for ovarian carcinoma." (PMID 35115587, 2022). "In ovarian cancer cells, EPCAM upregulation is connected to a more favorable prognosis and more effective platinum-based therapy." (PMID 35523936, 2022). "The anti-epithelial cell adhesion molecule (EpCAM) tagged bead scan can be used to obtain highly pure circulating tumor-derived exosomes of ovarian cancer and esophageal squamous cell carcinoma patients." (PMID 36051582, 2022). "In contrast, the cell aggregates found in most ovarian cancer samples contained a much higher (> 80%) percentage of tumor cells showing a strong EpCAM expression or combined EpCAM and CD24 positivity." (PMID 34060699, 2021). "In an attempt to explore the significance of CTC markers in ovarian cancer, we investigated the expression of EPCAM, MUC1, CEA, HE4 and CA125 mRNAs." (PMID 34006887, 2021). "In our recent study comparing IF and qPCR for the detection of CTCs in ovarian cancer patients, we achieved just moderate agreement by using a panel of antibodies for IF (including EpCAM) and cyclophilin C transcripts for the qPCR-based detection of CTCs." (PMID 34834576, 2021). "In 2008, Taylor and Gercel-Taylor were able to separate exosomes derived from ovarian cancer from serum samples by applying a modified magnetically activated cell sorting technique based on identifying the exosomal EpCAM protein using a LD microcolumn." (PMID 34940275, 2021). "The prognostic potential of epithelial (CD45-negative, cytokeratin-8, 18- and/or 19- and EpCAM-positive) CTCs in ovarian cancer was evaluated by several groups of researchers." (PMID 34440558, 2021). "The authors demonstrated high performance of the receiver operating characteristic (ROC) curve (ovarian cancer vs healthy control) with an area under curve (AUC) = 1 using either CA-125 or EpCAM as signature, and AUC = 0.91 for CD24." (PMID 34855021, 2021). "In particular, EpCAM-MC is a personalized APEC-immunotherapy for ovarian cancer that cleaves a CMV peptide (NLVPMVATV; abbreviated NLV) by tumor-expressed MMP7 and then is presented by MHCI (HLA-A*02:01)." (PMID 34415995, 2021).
ovarian carcinoma (continued). "Overexpression of human epidermal growth factor receptor 2 (HER2) and epithelial cell adhesion molecule (EpCAM) in approx. 30% and 70% of ovarian cancers, respectively, allows for co-targeted treatment." (PMID 34439094, 2021). "The human EpCAM protein has been shown to be highly expressed in many samples of human cancer (including ovarian cancer) and is considered a potential immunotherapeutic target for treatment." (PMID 34857007, 2021). "Here, animals were engrafted with GFP-expressing EpCAM+ OVCAR-5 ovarian carcinoma cells or chronic myelogenous leukemia K562 cells engineered to stably express human CD19 (K562-CD19)." (PMID 34415995, 2021). "In this work, we have investigated the use of Ec1-LoPE as the EpCAM-targeting component and the mAb trastuzumab as the HER2-targeting component for combination therapy of mice bearing HER2- and EpCAM-expressing SKOV3 ovarian cancer xenografts." (PMID 34439094, 2021). "Our extensive literature search did not reveal clinical data concerning co-expression of HER2 and EpCAM proteins in ovarian cancer, and we need to make estimations." (PMID 34439094, 2021). "EpCAM is an actively investigated therapeutic target in lung, gastric, colorectal, breast, and ovarian cancers." (PMID 34439094, 2021). "The authors isolated CTCs from the blood of 18 patients with ovarian cancer by an immunomagnetic method—using antibodies to EpCAM and mesenchymal N-cadherin." (PMID 34440558, 2021). "For example, the expression of EpCAM in patients with ovarian cancer depends on their histological subtypes." (PMID 33919456, 2021). "The number of CTSL1+ EPCAM+ cells and the expression level of CTSL1 in EPCAM+ cells were both higher in ovarian cancer tissues than in para-tumor tissues." (PMID 33933142, 2021). "Using CyTOF, CD24 was previously used to grade ovarian cancer, cytokeratin was applied in labeling melanoma cells, and EpCAM was recently selected for labeling of ovarian carcinoma cells." (PMID 35008313, 2021). "IL-8, together with IL-6, participates in the paracrine mechanism of expression regulation of the epithelial cell adhesion molecule (EpCAM), which contributes to tumor growth and whose overexpression occurs in ovarian cancer cells." (PMID 34572929, 2021). "EpCAM-MC was identified as the top APEC that kills ovarian carcinoma in a xenograft screen that used high content imaging of therapy responses in rag2Δ/Δ, il2rga−/− zebrafish (unpublished data)." (PMID 34415995, 2021). "High EPCAM expression was observed in CTSL1+ cells, indicating that CTSL1 within the ovarian cancer microenvironment was most likely derived from tumor cells (EPCAM+ cells)." (PMID 33933142, 2021). "Overall, 73% of ovarian cancers overexpress EpCAM, but serous ovarian cancers have a lower EpCAM overexpression rate (55%)." (PMID 33919456, 2021). "In fact, the beneficial role of EPCAM in prognosis had been observed in ovarian cancer and pancreatic cancer before." (PMID 34113647, 2021). "Monoclonal antibodies for epithelial cell adhesion molecule (EpCam) are under Phase 3 clinical trial in ovarian cancer immunotherapy." (PMID 33920983, 2021). "As an example, a 3D‐nanopatterned microfluidic chip allowed for the detection, in 2‐μL plasma samples from ovarian cancer patients, of exosome subpopulations expressing CD24, EpCAM and FR‐α proteins as potential biomarkers for ovarian cancer." (PMID 32666618, 2020). "Cell culture experiments with ovarian cancer cells which have different characters showed that coexpression of EpCAM, claudins and tetraspanin was related to ovarian cancer progression and also cisplatin resistance." (PMID 32091301, 2020). "In conclusion, the high activity and specificity observed in preclinical ovarian cancer models, combined with a high specificity in patient material, warrant a further investigation of EpCAM-targeted PDT for ovarian cancer." (PMID 32630661, 2020).
ovarian carcinoma (continued). "A slow internalization of Ec1 DARPin after binding to EpCAM on the surface of ovarian cancer cells determines good cellular retention of activity in the case of non-residualizing labels." (PMID 32392820, 2020). "Of note, high EpCAM expression has been identified as an independent parameter indicative of chemoresistance in an immunohistochemical analysis of 168 primary ovarian cancer tissues." (PMID 32438548, 2020). "Targeted photodynamic therapy (tPDT) aimed at epithelial cell adhesion molecule (EpCAM), overexpressed in over 90% of ovarian cancer metastatic lesions, is a promising novel therapeutic modality." (PMID 32630661, 2020). "For that, EpCAM positive CTCs were immunoisolated in a cohort of 38 patients with ovarian cancer and characterized using a panel of genes related to ovarian cancer aggressiveness and plasticity." (PMID 32423054, 2020). "After gradient centrifugation, three out of four samples were enriched for cells expressing ovarian cancer cell markers EpCAM or CA-125." (PMID 32200422, 2020). "This microfluidic chip was used for the rapid detection of exosomes expressing CD24, EpCAM and folate receptor α (FRα) in only 2 μL of plasma from ovarian cancer patients and healthy controls." (PMID 32226524, 2020). "Here, we tested the specificity and activity of conjugates of EpCAM-directed designed ankyrin repeat proteins (DARPins) with the photosensitizer IRDye 700DX in in vitro and in vivo ovarian cancer models." (PMID 32630661, 2020). "The expression patterns of EpCAM, claudins, E-cadherin and tetraspanins were investigated compared within ovarian cancer cell lines, A2780, OVCAR-3, SKOV-3 and A2780cis." (PMID 32091301, 2020). "Consistent with our results, ovarian cancers with high levels of EpCAM had significantly much lower responsive rates after first-line chemotherapy." (PMID 32091301, 2020). "The secondary goal was to evaluate if EpCAM on ovarian cancer xenografts is sufficiently accessible to permit DARPin-mediated delivery of cytotoxic payload." (PMID 32392820, 2020). "One study has demonstrated that the level of EpCAM+ exosome is positively correlated with the ovarian cancer stage and aggressiveness." (PMID 32046162, 2020). "Conjugation of anti-EpCAM DARPins with fluorophores maintained EpCAM-specific binding in cell lines and patient-derived ovarian cancer explants." (PMID 32630661, 2020). "EpCAM-siPKCι aptamer not only effectively induced apoptosis of PRKCI-amplified ovarian cancer cells but also greatly deterred intraperitoneal tumor development in xenograft mouse model." (PMID 32820156, 2020). "In this study, we showed the feasibility and specific phototoxic activity of IRDye 700DX coupled to EpCAM-targeting DARPins for targeted PDT in ovarian cancer." (PMID 32630661, 2020). "Both EpCAM-targeting DARPins, Ec1 and Ac2, showed binding and the ability to effectively induce cell death in both 2D and 3D models of epithelial ovarian cancer." (PMID 32630661, 2020). "Taken together, ovarian cancer frequently expresses a complex of EpCAM, claudin-4 or −7 and CD82 that is located in TEMs." (PMID 32091301, 2020). "A combination of devices coated with anti-EpCAM or anti-fibroblast activation protein alpha (FAPα) antibodies were applied for patients with several kinds of cancers including ovarian cancer." (PMID 33327605, 2020). "The finding that EpCAM aptamer-delivered PKCι siRNA selectively induces apoptosis in PRKCI-amplified ovarian cancer cells led us to further investigate the efficacy of EpCAM-siPKCι aptamer to suppress ovarian tumor progression." (PMID 32820156, 2020). "Although a number of markers on EVs have been identified for a particular type of tumour (for example: EpCAM for ovarian cancer; VLA-4, TYRP2 and MET for melanoma; MIF for PDAC), so far, no universal markers have been found." (PMID 33081785, 2020).